EBF1 (EBF transcription factor 1)
Diseases named in the same sentence as EBF1 in open-access papers (continued):
Sharing a sentence is not in itself a finding about the gene and the disease.
cognitive disorder (2 papers, 2018 to 2024). A disease affects cognitive processes. "Currently, the role and mechanism of EBF1 in cognitive disorders and AD are unclear, and more experiments are needed to clarify the role of EBF1 in the future." (PMID 39347016, 2024).
COVID-19 (2 papers, 2021). A disease caused by infection with severe acute respiratory syndrome coronavirus 2. "However, for any number of reasons, “floxing away” EBF1 from adipocytes in humans—even if it were feasible at this time—seems questionable, whereas global lack of EBF1 would likely severely compromise an obese patient’s immune system, all the more undesired with the current COVID-19 pandemic." (PMID 33732506, 2021). "In all, 8 out of 107 HSC/MPP cells in HC and 2 out of 77 HSC/MPP cells in COVID-19 patients with mild disease expressed ID3, but not in severe cases, although PAX5 and EBF1 were not identified." (PMID 34349096, 2021).
deafness (2 papers, 2024 to 2025). An inherited or acquired condition characterized by the complete loss of the ability to hear from one or both ears. "We previously showed that conditional deletion of Ebf1 in the inner ear causes deafness." (PMID 41442958, 2025). "Their findings agree with those we detail in this report and further support an important role for EBF1 in development of the organ of Corti and suggest its mutation might cause deafness in humans." (PMID 39037017, 2024). "In summary, we have identified EBF1 as a key factor for patterning the mammalian cochlea and deletion of Ebf1 leads to deafness in mice." (PMID 39037017, 2024).
diabetes (2 papers, 2017 to 2020). "Previous studies have shown EBF1 regulates blood glucose and lipid metabolism in mice with diabetes and central adiposity." (PMID 28183271, 2017).
glioblastoma (2 papers, 2021 to 2025). The most malignant astrocytic tumor (WHO grade IV). "Immunostaining performed on human glioblastoma samples showed that the constitutive elements of these glomeruloid structures are represented by EBF1-expressing pericytes, as reported." (PMID 34272603, 2021). "In order to detect the phenotype of EBF1-expressing cells, we thus performed double immunostaining of glioblastoma samples using a specific antibody for EBF1 combined with lineage-specific markers." (PMID 34272603, 2021). "For this reason, since we used glioblastoma as a model to characterize the phenotype of EBF1-expressing cells, we also investigated EBF1 expression in HBVPs." (PMID 34272603, 2021). "In order to investigate the functional role of EBF1 in pericytes, we exposed HBVPs and PL-PCs (not shown) to different culture conditions, i.e. hypoxia, nutrient starvation and medium obtained from U87 glioblastoma cells cultured under hypoxic and normoxic conditions." (PMID 34272603, 2021). "However, we wondered whether expression of EBF1 was restricted to glioblastoma vessels or was indeed a common feature of tumor vessels." (PMID 34272603, 2021). "Since the anti-pan-EBF antibody recognizes all four EBF proteins, we employed specific antibodies for the different molecules, EBF1–4, and observed that the glomeruloid glioblastoma vessels selectively expressed EBF1." (PMID 34272603, 2021). "Moreover, EBF1+ cells did not express GFAP, a well-recognized marker of glioblastoma." (PMID 34272603, 2021).
Hypoglycemia (2 papers, 2017 to 2018). A decreased concentration of glucose in the blood. "In vivo experimental studies have shown hypoglycemia, and low-fat metabolic syndrome occurred after knockout of EBF1 in mice." (PMID 29789399, 2018). "Similarly, after knocking out the EBF1 in mice, the mice were found to have symptoms such as abnormal fat metabolism, hypoglycemia, and other symptoms." (PMID 29789399, 2018).
Insulin resistance (2 papers, 2015 to 2021). Increased resistance towards insulin, that is, diminished effectiveness of insulin in reducing blood glucose levels. "Changes in adipose EBF-1 expression is linked to abnormal metabolic function of fat cells and to in vivo insulin resistance." (PMID 26423009, 2015).
lung carcinoma (2 papers, 2019 to 2022). "Likewise, EBF1 and RUNX1 also appear in the LCII network, and they are also in the LCI coexpression network, probably strengthening their importance and association with the progression of some types of lung cancer." (PMID 36101460, 2022).
mantle cell lymphoma (2 papers, 2022 to 2024). Mantle cell lymphoma is a rare form of malignant non-Hodgkin lymphoma affecting B lymphocytes in the lymph nodes in a region called the ``mantle zone''. "Through screening for molecular vulnerabilities of mantle cell lymphoma (MCL), we identified a set of transcription factors (TFs) including FOXO1, EBF1, PAX5, and IRF4 that are essential for MCL propagation." (PMID 36282572, 2022).
sarcoma (2 papers, 2019 to 2022). A usually aggressive malignant neoplasm of the soft tissue or bone. "Mechanistically, we found that Ebf1-KRAB-expressing sarcoma cells exhibit a reduced enrichment of EWS/ATF1 at the super-enhancer when compared with the control NANOG-KRAB-expressing sarcoma cells." (PMID 31488818, 2019). "Consistently, Cdkn1a and Ink4a, as well as Il-6, were upregulated in Ebf1-KRAB-expressing sarcoma cells when compared with control NANOG-KRAB-expressing sarcoma cells." (PMID 31488818, 2019). "In addition, it was verified through TCGA database that EBF1 was up-regulated in sarcoma tissue samples." (PMID 35761386, 2022). "Moreover, consistent with our finding that EWS/ATF1 actively prevents premature senescence in sarcoma cells, SA β-gal-positive cells were increased in Ebf1-KRAB-expressing sarcoma cells." (PMID 31488818, 2019). "Notably, the introduction of the Ebf1-KRAB fusion gene resulted in remarkable growth inhibition of sarcoma cells, whereas the transduction of control KRAB fusion genes did not inhibit the growth of sarcoma cells." (PMID 31488818, 2019). "Importantly, knockdown of Ebf1 did not affect sarcoma cell growth, suggesting that enhancer activity at Ebf1 binding sites, but not Ebf1 expression itself, has an impact on the growth of sarcoma cells." (PMID 31488818, 2019).
Varicose veins (2 papers, 2025). Enlarged and tortuous veins. "The second CCL5-related TF, EBF1, is implicated in blood pressure and inflammation, and its genetic variants were previously associated with varicose veins in a large-scale genetic study." (PMID 41009355, 2025).
viral infection (2 papers, 2022 to 2025). "For example, a survey of multiple different LCL lines found that high level expression of EBF1 is inversely correlated with lytic viral infection, and this inverse correlation is greater for EBF1 than for any other cellular gene." (PMID 35472072, 2022). "Whether EBF1 would play a similar role in viral infection of BRD pathogens is unknown but further study is warranted." (PMID 40822650, 2025).
anxiety disorder (1 paper, 2025). A category of psychiatric disorders which are characterized by anxious feelings or fear often accompanied by physical symptoms associated with anxiety. "Common genetic variants for Ebf1 are associated with anxiety disorders and anorexia nervosa." (PMID 41116115, 2025). "Ebf1 mutations are associated with anxiety disorders and anorexia nervosa." (PMID 41116115, 2025).
autonomic dysfunction (1 paper, 2017). "Both our data and the available published research support a role for Ebf1 in the mechanisms underlying autonomic dysfunction, thereby suggesting a novel hypothesis for a genetic contribution to autonomic dysfunction development." (PMID 28732007, 2017).
B-cell neoplasm (1 paper, 2017). A group of heterogeneous lymphoid tumors generally expressing one or more B-cell antigens or representing malignant transformations of B-lymphocytes. "Loss of EBF1 protein was observed in other spontaneous pre-B-cell neoplasms, such as those that develop from B cells in transgenic Eμ-Myc mice, which overexpress cMyc (last three lanes)." (PMID 28692033, 2017).
bladder urothelial carcinoma (1 paper, 2020). "DNA sequencing and qRT-PCR of urine specimens confirmed that EBF1 was different between bladder urothelial carcinoma and normal tissues, but this difference did not exist in upper urinary tract tumors, suggesting that EBF1 may be bladder-specific." (PMID 32420368, 2020).
brain neuroblastoma (1 paper, 2022). "On the contrary, EBF1 (z = −11.34) and GNG7 (z = −5.813) were the brain neuroblastoma- and lung adenocarcinoma-specific positive prognostic genes, respectively." (PMID 35634306, 2022).
breast tumor (1 paper, 2025). "Conversely, breast tumor displayed an overall repressed state of the EBF1 gene, as indicated by DNA hypermethylation, and repressive H3K27me3 modification." (PMID 39796183, 2025).
cardiac hypertrophy (1 paper, 2024). "ChIP-seq further unveiled EBF1 occupancy on promoters of genes linked to cardiac hypertrophy, including MEF2C and NPPA/NPPB." (PMID 39239522, 2024). "Our study's findings not only illuminate the role of EBF1 in controlling cardiac development but also unveil its involvement in cardiac hypertrophy." (PMID 39239522, 2024). "Mechanistically, we found that EBF1 directly bound to upstream chromatin regions of cardiac hypertrophy-inducing genes, contributing to cardiac hypertrophy." (PMID 39239522, 2024). "We found that Ebf1+/- mice developed cardiac hypertrophy and fibrosis." (PMID 39239522, 2024). "Thus, this evidence demonstrated that EBF1 depletion instigates cardiac hypertrophy, which are similar with some phenotypes reported in the public database (informatics.jax.org/marker/MGI:95275)." (PMID 39239522, 2024). "Accordingly, we postulated that EBF1 might play a role in cardiac hypertrophy." (PMID 39239522, 2024). "Therefore, the diminished binding of EBF1 to the MEF2C promoter resulted in heightened MEF2C transcription within cardiomyocytes, thereby contributing to the development of cardiac hypertrophy." (PMID 39239522, 2024).
cardiomyopathy (1 paper, 2024). A disease of the heart muscle or myocardium proper. "The transcriptomic analysis unveiled significant transcriptional perturbations induced by Ebf1+/-, with up-regulated genes linked to cardiomyopathy." (PMID 39239522, 2024). "Except for the perturbated genes in cardiomyopathy, EBF1 knockout also perturbed genes governing oxidative phosphorylation, ATP synthesis coupled electron transport and the cardiac muscle contraction." (PMID 39239522, 2024). "Thus, our findings demonstrated that EBF1 depletion induces transcriptional perturbations in adult mouse heart, which may lead to cardiomyopathy." (PMID 39239522, 2024).
diphtheria (1 paper, 2021). A Gram-positive bacterial infection caused by Corynebacterium diphtheriae. "Using single-cell RNASeq following tetanus/diphtheria immunization of offspring, we identified a defect in cell-cycle and cell-proliferation pathways in addition to a reduction in Ebf-1, a key B-cell transcription factor, in the majority of follicular B cells." (PMID 33524040, 2021).
dyslipidemia (1 paper, 2012). "This may suggest that EBF1 has a similar role in regulating adiposity and lipid metabolism in humans, and that variants in the gene may represent good candidate polymorphisms for cardiovascular disease and dyslipidemia in humans." (PMID 22369142, 2012).
Hodgkins lymphoma (1 paper, 2016). A heterogeneous group of malignant lymphoid neoplasms of B-cell origin characterized histologically by the presence of Hodgkin and Reed-Sternberg (HRS) cells in the vast majority of cases. "For example, reduced expression of early B-cell factor 1 (EBF1) has been found in Hodgkin lymphoma and appears to contribute to the loss of B-cell phenotype and consequent malignancy." (PMID 27144453, 2016).
Huntington disease (1 paper, 2020). Huntington disease (HD) is a rare neurodegenerative disorder of the central nervous system characterized by unwanted choreatic movements, behavioral and psychiatric disturbances and dementia. "Ebf1 is expressed in the lateral ganglionic eminence (LGE), which generates striatal projection neurons, including medium spiny neurons that are preferential lost in Huntington’s disease." (PMID 32912160, 2020).
hypertrophic cardiomyopathy (1 paper, 2024). A condition in which the myocardium is hypertrophied without an obvious cause. "Additionally, we found that EBF1 was significantly downregulated in hypertrophic cardiomyopathy (HCM) heart tissues and myocardial infraction (MI) heart tissues, compared to healthy heart tissues, respectively." (PMID 39239522, 2024).
intervertebral disc degeneration (1 paper, 2024). "An in vivo study demonstrates that circEYA3 plays an important role in exacerbating the progression of intervertebral disc degeneration by modulating the NF-κB signalling pathway through regulation of the miR196a-5p/EBF1 axis." (PMID 38555395, 2024).
liver cancer (1 paper, 2021). An epithelial or non-epithelial malignant neoplasm that arises from the liver. "In liver cancer, hsa_circ_0074817| EBF1 targets miR-539-5p, targeting CDK4 and SPAG5." (PMID 34055888, 2021).
lymphoid neoplasm (1 paper, 2024). A neoplasm composed of a lymphocytic cell population which is usually malignant (clonal) by molecular genetic and/or immunophenotypic analysis. "Previous studies have demonstrated that aberrant modulation of EBF1, ETS1, ERG, and RUNX transcription factors has significant effects on lymphoid neoplasms derived from B cell progenitors." (PMID 38926853, 2024).
male pattern baldness (1 paper, 2025). "Genome-wide association studies have reported that two single-nucleotide polymorphisms (rs929626 and rs1081073) of the transcription factor EBF1 (early B-cell factor 1) are associated with male pattern baldness." (PMID 39498465, 2025).
melanoma (1 paper, 2022). A malignant, usually aggressive tumor composed of atypical, neoplastic melanocytes. "SNP variants in Ebf1 were likewise associated with IL-12 p40 blood levels in humans with Stage I melanoma, and SNP in both IL17B and Ebf1 were associated with melanoma susceptibility and patient outcomes." (PMID 35591856, 2022).
non-Hodgkin lymphoma (1 paper, 2023). Distinct from Hodgkin lymphoma both morphologically and biologically, non-Hodgkin lymphoma (NHL) is characterized by the absence of Reed-Sternberg cells, can occur at any age, and usually presents as a localized or generalized lymphadenopathy associated with fever and weight loss. "In non-Hodgkin’s lymphoma (NHL), four out of five Supertargets (myocyte enhancer factor 2B (MEF2B), EBF transcription factor 1 (EBF1), BCL6 transcriptional repressor (BCL6), and paired box 5 (PAX5)) encode well-studied transcription factors with significant roles in B-cell malignancies." (PMID 37297004, 2023).
oral squamous cell carcinoma (1 paper, 2024). "EBF1 was shown to be targeted by miR-19a-in oral squamous cell carcinoma." (PMID 38539461, 2024).
osteosarcoma (1 paper, 2022). A usually aggressive malignant bone-forming mesenchymal neoplasm, predominantly affecting adolescents and young adults. "EBF1 induced-FGA5-AS1 aggravated osteosarcoma cell malignancy by targeting miR-124-3p and G3BP2." (PMID 35761386, 2022). "Next, we detected the biological function of EBF1 on osteosarcoma cells." (PMID 35761386, 2022). "Furthermore, we identified EBF transcription factor 1 (EBF1) as the transcription factor for FGA5-AS1, and EBF1 served as a tumor facilitator in osteosarcoma cells." (PMID 35761386, 2022).
ovarian carcinoma (1 paper, 2024). A malignant neoplasm originating from the surface ovarian epithelium. "These genes have links to several other women’s health conditions: EBF1 mRNA have been associated with spontaneous preterm birth 20, FAM120B21 and ABO 22 have both been found to be related to ovarian cancer." (PMID 39315247, 2024).
Sepsis (1 paper, 2012). Sepsis is defined as life-threatening organ dysfunction caused by a dysregulated host response to infection. "Transcriptional regulators like PLAGL2, EBF1, TCF7, KLF10 and SBNO2, previously not described in sepsis, are differentially expressed at early and late time points." (PMID 23009705, 2012).
trisomy 21 (1 paper, 2023). A chromosomal disorder consisting of the presence of an extra chromosome 21. "Methylation of members of this gene family have been associated with a number of phenotypes, including EBF4 methylation associated with hematopoiesis and neuronal development in persons with Trisomy 21, and EBF1 and EBF3 methylation to neurobehavioral development in very preterm infants." (PMID 36959629, 2023).